MAP7D3 (MAP7 domain containing 3)
Description:
Promotes the assembly and stability of microtubules.
Synonyms: MDP3; FLJ12649
Tractability: PROTAC: ubiquitination databases record sites on it; its protein half-life has been measured.
Gene: Protein-coding gene on chromosome X (136,213,220 to 136,256,482, reverse strand). Ensembl gene ENSG00000129680.
Subcellular location: Cytoplasm, cytoskeleton, spindle
Subcellular location (Human Protein Atlas): Centrosome; Plasma membrane; Basal body; Nucleoplasm; Primary cilium
Gene Ontology:
Molecular function: microtubule binding; tubulin binding
Biological process: microtubule cytoskeleton organization; microtubule polymerization
Cellular component: membrane; microtubule cytoskeleton; spindle
Homologues: Orthologues: chimpanzee MAP7D3 (99% identical), macaque MAP7D3 (93% identical), dog MAP7D3 (55% identical), rat Map7d3 (28% identical), mouse Map7d3 (25% identical), zebrafish map7d3 (25% identical), tropical clawed frog map7d3 (24% identical), Drosophila melanogaster ens (16% identical). Paralogues in human: MAP7D1 (19% identical), MAP7 (18% identical), MAP7D2 (18% identical).
Diseases named in the same sentence as MAP7D3 in open-access papers:
MAP7D3 is named in the same sentence as 11 diseases in open-access papers, as found by Europe PMC text mining. Sharing a sentence is not in itself a finding about the gene and the disease. The quoted sentences say what the papers report.
breast carcinoma (3 papers, 2020 to 2023). "In this study, we utilized the UCSC Xena platform to analyze the TCGA breast cancer dataset and found that MAP7D3 expression was significantly correlated with TNBC patients." (PMID 37550720, 2023). "Clinically, we demonstrated that high levels of MAP7D3 expression were significantly correlated with TNBC among other breast cancer subtypes." (PMID 37550720, 2023). "While its homologue MAP7D3 promotes breast cancer growth and metastasis in mice, the role of MAP7D1 in cancer metastasis remained unclear yet." (PMID 33716151, 2021). "Next, we investigated if MAP7D3 depletion could alter the expression of proteins related to chemoresistance phenotype of breast cancer." (PMID 37550720, 2023). "Moreover, MAP7D3 depletion could significantly retard primary tumor growth and inhibit lung metastasis capability of metastatic TNBC cells in the orthotopic breast cancer mouse model and tail-vein injection mouse model, respectively." (PMID 37550720, 2023).
autism spectrum disorder (1 paper, 2014). A spectrum of developmental disorders that includes autism, and Asperger syndrome. "MAP7D3 has not been associated with autism spectrum disorders." (PMID 24690944, 2014).
lymph node metastasis (1 paper, 2023). "Analysis of our in-house TNBC cohort samples indicated that lymph node metastatic tumors exhibited a greater expression of MAP7D3 than their corresponding primary tumors." (PMID 37550720, 2023).
mental retardation (1 paper, 2014). "There was one report of a truncating variant in MAP7D3 in an X-linked mental retardation family that did not segregate with disease." (PMID 24690944, 2014).
metastatic tumors (1 paper, 2023). "qRT-PCR results showed that the expression of MAP7D3 was upregulated in 63.8% of LN metastatic tumors (23/36) when compared with the matched primary tumors, indicating that MAP7D3 plays an essential role in TNBC metastatic progression." (PMID 37550720, 2023). "Moreover, our investigation of paired primary tumors and LN metastatic tumors revealed that 63.8% of TNBC patients exhibited higher expression of MAP7D3, which was in line with our cell-based experiments." (PMID 37550720, 2023).
neuroblastoma (1 paper, 2022). Neuroblastoma (NB) is the most common solid, extracranial childhood tumor. "We also examined the cellular functions of Map7D2 using the N1-E115 mouse neuroblastoma cell line, which expresses both Map7D2 and Map7D1 but not Map7 nor Map7D3." (PMID 35470240, 2022). "For this experiment, we used a mouse neuroblastoma cell line, N1-E115, in which the expression of Map7d2 and Map7d1, but not Map7 and Map7d3, was detected by quantitative real-time PCR (RT-qPCR)." (PMID 35470240, 2022).
prostate adenocarcinoma (1 paper, 2024). "To ascertain the differential expression and prognostic significance of MAP7D3 in prostate adenocarcinoma (PRAD), we conducted immunohistochemistry experiments on 60 PRAD samples and their corresponding normal prostate tissue samples." (PMID 38817605, 2024).
triple-negative breast carcinoma (1 paper, 2023). An invasive breast carcinoma which is negative for expression of estrogen receptor (ER), progesterone receptor (PR), and human epidermal growth factor receptor 2 (HER2). "Our research has identified the novel role of MAP7D3 in regulating the progression of triple-negative breast cancer (TNBC)." (PMID 37550720, 2023). "Our study indicates that targeting MAP7D3 could be a promising therapeutic strategy for addressing the progression of TNBC, and MAP7D3 may serve as a novel predictive biomarker for the survival outcomes of triple-negative breast cancer." (PMID 37550720, 2023).
cancer (4 papers, 2019 to 2024). A tumor composed of atypical neoplastic, often pleomorphic cells that invade other tissues. "Comparing 60 cases of cancer with 60 adjacent cancer cases, we observed significantly higher MAP7D3 expression in the cancer samples." (PMID 38817605, 2024). "Functional assays indicated that depletion of MAP7D3 expression significantly inhibited the ability of cancer cell migration, invasion, and 3D colony formation." (PMID 37550720, 2023). "Knockdown of MAP7D3 expression effectively suppressed in vitro metastasis traits of highly metastatic TNBC cells including cancer cell migration, invasion, and anchorage-independent growth and sensitized TNBC cells to standard chemo drug treatment such as docetaxel and gemcitabine." (PMID 37550720, 2023).
tumor (2 papers, 2023 to 2024). "Collectively, our clinical findings provide first evidence to demonstrate the clinical relevance of MAP7D3 in TNBC that high expression of MAP7D3 is associated with tumor progression, LN metastasis, and poor survival outcomes of TNBC patients." (PMID 37550720, 2023). "Further categorizing the samples based on high and low MAP7D3 expression levels, we discovered a significant correlation between MAP7D3 expression, tumor invasion, and patient survival status." (PMID 38817605, 2024). "Detailed examination of tumor invasion and patient survival status in the high and low MAP7D3 expression groups revealed distinct patterns." (PMID 38817605, 2024). "The animal study showed that the depletion of MAP7D3 drastically reduced TNBC tumor growth and impaired the metastatic capability of TNBC cells." (PMID 37550720, 2023). "Our animal study showed that MAP7D3 depletion effectively suppressed TNBC tumor growth and metastatic progression in the orthotopic TNBC mouse model." (PMID 37550720, 2023). "Specifically, inhibiting the expression of MAP7D3 resulted in a substantial impairment of primary tumor growth and a decrease in the potential for distant lung metastasis in metastatic TNBC cells." (PMID 37550720, 2023). "Next, we examined the mRNA levels of MAP7D3 in our cohort samples containing 36 paired lymph node (LN) metastasis tissues and primary tumor tissues." (PMID 37550720, 2023). "Tumor growth kinetics analysis showed that MAP7D3 depletion effectively inhibited tumor growth of IV2 cells." (PMID 37550720, 2023). "In addition, the mouse study confirmed that MAP7D3 expression was essential for TNBC progression that inhibition of MAP7D3 suppressed primary tumor growth and distant lung metastasis of metastatic TNBC cells." (PMID 37550720, 2023). "First, the control IV2 cells and MAP7D3-depleted IV2 cells were orthotopically injected into the mouse fat pad and the tumor growth kinetics was analyzed for 8 weeks." (PMID 37550720, 2023).
MAP7D3 also shares sentences with these, for which no sentence is quoted: ischemic stroke (1 paper).